OR4C11 (olfactory receptor family 4 subfamily C member 11)
Description:
Odorant receptor.
Synonyms: OR4C11P; OR11-136
Tractability: Antibody: UniProt places it where antibodies can reach, with medium confidence; UniProt predicts a signal peptide or a membrane-spanning region; its Gene Ontology location is reachable by antibodies, with medium confidence.
Gene: Protein-coding gene on chromosome 11 (55,602,360 to 55,607,645, reverse strand). Ensembl gene ENSG00000172188.
Subcellular location: Cell membrane
Pathways (Reactome):
Sensory Perception: Expression and translocation of olfactory receptors
Gene Ontology:
Molecular function: olfactory receptor activity; G protein-coupled receptor activity
Biological process: detection of chemical stimulus involved in sensory perception of smell; G protein-coupled receptor signaling pathway
Cellular component: plasma membrane; membrane
Genetic constraint (gnomAD): Loss-of-function variants: 11 observed, 7.6 expected, observed/expected ratio (o/e) 1.45, 90% interval 0.88 to 1.92. That is too few expected variants to judge how well the gene tolerates losing a copy. Missense variants: 206 observed, 174.25 expected, observed/expected ratio (o/e) 1.18, 90% interval 1.05 to 1.33. Synonymous variants: 67 observed, 59.27 expected, observed/expected ratio (o/e) 1.13, 90% interval 0.93 to 1.38.
Homologues: Orthologues: dog OR4C11I (90% identical), rat Or4c11 (89% identical), mouse Or4c11 (88% identical), dog OR4C11 (87% identical), dog OR4C11J (86% identical), guinea pig OR4C11 (86% identical), dog OR4C11L (85% identical), mouse Or4c11b (84% identical), mouse Or4c11c (84% identical), rabbit OR4C11 (74% identical). Paralogues in human: OR4C16 (67% identical), OR4C15 (58% identical), OR4C12 (57% identical), OR4C46 (57% identical), OR4A15 (56% identical), OR4S2 (56% identical), OR4C3 (55% identical), OR4A47 (55% identical), OR4A5 (55% identical), OR4C13 (55% identical), OR4X2 (55% identical), OR4B1 (55% identical), and 116 more.
Diseases named in the same sentence as OR4C11 in open-access papers:
OR4C11 is named in the same sentence as 4 diseases in open-access papers, as found by Europe PMC text mining. Sharing a sentence is not in itself a finding about the gene and the disease. The quoted sentences say what the papers report.
breast carcinoma (3 papers, 2017 to 2021). "A genome-wide analysis of CNVs identified deletions at the OR4C11/OR4P4 locus that were also associated with breast cancer risk." (PMID 28302160, 2017). "Moreover, other common CNVs were found to be associated with breast cancer risk through whole genome CNV genotyping studies including those disrupting OR4C11, OR4P4, OR4S2 and UGT2B17 genes." (PMID 33503040, 2021). "Association tests of CNVs, followed by experimental validation of CNV calls, found deletions overlapping the OR4C11 and OR4P4 genes were associated with breast cancer (P = 0.02 and P = 0.03, respectively)." (PMID 28302160, 2017). "Indeed, this patient harbored several CNVs reported as associated with breast cancer risk involving UGT2B17, OR4C11, OR4P4, OR4S2 and GSTT1 genes." (PMID 33503040, 2021). "A genome-wide association study of the cases and controls identified deletions overlapping three gene regions (DOCK5, 6.9-fold, P = 0.003; OR4C11, 2.6-fold, P = 0.02, and OR4P4, 2.4-fold, P = 0.03) that were associated with an increased risk of breast cancer after accounting for multiple testing." (PMID 28302160, 2017). "We have replicated CNVs (n = 5) from the familial breast cancer study, including CNVs in genes ANKS1B19, OR4C11, OR4P4, UGT2B17, OR4C6, OR4S215." (PMID 29116104, 2017). "Deletions in three genes were associated with increased risk of breast cancer (DOCK5, P = 3 × 10-3; OR4C11, P = 2 × 10-2; and OR4P4, P = 3 × 10-2). qPCR did not confirm the small 646-base-pair deletion at the DOCK5 locus." (PMID 28302160, 2017).
OR4C11 also shares sentences with these, for which no sentence is quoted: breast tumour (1 paper); cancer (1); Obesity (1).